DDX21 (DExD-box helicase 21)
Diseases named in the same sentence as DDX21 in open-access papers (continued):
Sharing a sentence is not in itself a finding about the gene and the disease.
leukemia (2 papers, 2021). A malignant (clonal) hematologic disorder, involving hematopoietic stem cells and characterized by the presence of primitive or atypical myeloid or lymphoid cells in the bone marrow and the blood. "DDX21 also forms a protein complex with the leukemogenic Amino‐terminal Enhancer of Split protein, and DDX21 knockdown has been shown to reduce leukemia cell proliferation and clonogenesis." (PMID 33497018, 2021). "Notably, the knockdown of Ddx21 phenocopies the depletion of Aes by reducing growth capacity of leukemia cells." (PMID 33946178, 2021).
ovarian carcinoma (2 papers, 2022 to 2024). A malignant neoplasm originating from the surface ovarian epithelium. "When PARP1-mediated ADPRylation of DDX21 is inhibited by niraparib, DDX21 is mislocalized to the nucleoplasm resulting in decreased rDNA transcription, which leads to a reduction in ribosome biogenesis, protein translation, and ultimately endometrial and ovarian cancer cell growth." (PMID 38767454, 2024).
bipolar disorder (1 paper, 2018). A disorder of the brain that causes unusual shifts in mood, energy, activity levels and the ability to carry out day-to-day tasks. "Two other targeted genes happened to be DE in the anterior cingulate of bipolar disorder patients vs controls: DDX21 (adjusted P-value < 0.00012; logFC = −0.7) and NUCKS1 (adjusted P-value < 0.1; logFC = −0.28)." (PMID 29745862, 2018). "We identified four rSNP-targeted genes that showed differential expression between patient and control groups depending on brain region: NRAS—in schizophrenia cohort, CDC25B, DDX21 and NUCKS1—in bipolar disorder cohort." (PMID 29745862, 2018).
bladder cancer (1 paper, 2024). "It is noteworthy that DDX21 has been associated with bladder cancer in several studies, but there are no mechanistic studies evaluating its involvement." (PMID 39132499, 2024).
colitis (1 paper, 2026). Inflammation of the colon. "Consequently, Ddx21-deficient CD4+ T cells exhibit resistance to inducing adoptive transfer colitis, with recipients showing reduced T cell infiltration compared to wild-type (WT) counterparts." (PMID 42210780, 2026).
COVID-19 (1 paper, 2021). A disease caused by infection with severe acute respiratory syndrome coronavirus 2. "In our analysis, the component DDX21 was upregulated in MSCs from severe over mild COVID-19 cases." (PMID 35095855, 2021).
endometrial cancer (1 paper, 2024). Primary or metastatic malignant neoplasm involving the endometrium (mucous membrane that lines the endometrial cavity). "By studying endometrial cancer patient samples, we were able to show that high DDX21 nucleolar localization was significantly associated with decreased survival." (PMID 38767454, 2024).
HCMV infection (1 paper, 2022). "For example, during HCMV infection, DDX21 reduces the accumulation of R-loops, which promotes the transcription of HCMV late genes, consequently resulting in the promotion of HCMV growth." (PMID 35336874, 2022).
keloid (1 paper, 2023). An irregularly shaped, elevated mark on the skin caused by deposits of excessive amounts of collagen during wound healing. "DDX21 may be involved in processes related to transcription regulation and RNA processing, thereby influencing molecular pathways and signal transduction associated with the development of keloids." (PMID 37988222, 2023). "In the development of keloids, the regulation of RNA synthesis and stability may be involved, and DDX21 is suggested to play a role in these processes." (PMID 37988222, 2023).
kidney chromophobe (1 paper, 2022). "However, DDX21 expression was dramatically reduced in KICH (kidney chromophobe), KIRP (kidney renal papillary cell carcinoma), and KIRC (kidney renal clear cell carcinoma)." (PMID 36505822, 2022).
lentivirus infection (1 paper, 2022). Virus diseases caused by the Lentivirus genus. "DDX21 was overexpressed after lentivirus infection, and cell proliferation was dramatically boosted." (PMID 36505822, 2022).
lung adenocarcinoma (1 paper, 2022). A carcinoma that arises from the lung and is characterized by the presence of malignant glandular epithelial cells. "Furthermore, Cell Counting Kit-8 (CCK-8) and Transwell studies were employed to assess the effect of DDX21 expression on lung adenocarcinoma (LUAD) cell proliferation and migration." (PMID 36505822, 2022).
lymph node metastasis (1 paper, 2025). "Furthermore, CRC patients with metastasis (including distant and lymph node metastasis) exhibited increased DDX21 expression." (PMID 40301349, 2025).
metastatic tumor (1 paper, 2023). "Third, IHC of E-cadherin and vimentin in liver metastatic tumor, lung metastatic tumor and soft tissue metastatic tumor models revealed that loss of DDX21 enhanced E-cadherin but reduced vimentin expression." (PMID 37029300, 2023).
mucinous carcinoma (1 paper, 2020). "However, positive DDX21 expression was significantly more prominent in non-mucinous carcinoma (32.2%) vs. mucinous carcinoma (13.0%)." (PMID 33328538, 2020).
osteosarcoma (1 paper, 2022). A usually aggressive malignant bone-forming mesenchymal neoplasm, predominantly affecting adolescents and young adults. "The genes DDX24, DDX21, WARS, and IGF2BP2 might play a pivotal role in osteosarcoma, and these genes will be considered as therapeutic targets for osteosarcoma treatment." (PMID 36140189, 2022).
stomach disease (1 paper, 2025). "DDX21 was first isolated as a nucleolar RNA helicase recognized by autoantibodies from a patient with watermelon stomach disease." (PMID 39866844, 2025).
uterine corpus endometrial carcinoma (1 paper, 2022). A endometrial carcinoma (disease) that involves the body of uterus. "DDX21 mutations were most common in uterine corpus endometrial carcinoma (UCEC; >5%), and DDX21 expression was positively correlated with the degree of infiltration of CAF and CD8+ cells in several tumor types." (PMID 36505822, 2022).
cancer (32 papers, 2008 to 2025). A tumor composed of atypical neoplastic, often pleomorphic cells that invade other tissues. "Alterations in DDX21 regulation have been linked to various types of cancer, highlighting its potential as both a biomarker and a therapeutic target." (PMID 39769343, 2024). "DDX21 is overexpressed in a variety of cancers, and overexpression in some cancers is associated with poor prognosis." (PMID 36505822, 2022). "In summary, DDX21 is commonly overexpressed in a variety of cancers, and its gene expression is statistically linked with some clinical outcomes in some patients." (PMID 36505822, 2022). "The DDX21 gene was highly expressed in most cancers, and overexpression was associated with poor overall survival (OS) and disease-free survival (DFS)." (PMID 36505822, 2022). "Secondly, this research only presents early evidence associating DDX21 with cancer progression in a variety of tumors." (PMID 36505822, 2022). "Contrarily, “open” DDX21 conformation due to SLERT depletion causes an increase of DDX21-Pol I association coupled with diminishing of Pol I transcription that leads to reduced proliferation of cancer cells." (PMID 31269716, 2019). "High PARP1 expression was associated with high nucleolar localization of DDX21 in both cancers." (PMID 38767454, 2024). "An aberrant expression of DDX21 was observed in several cancers, with somewhat opposite roles depending on the specific context examined." (PMID 40002164, 2025). "Our bioinformatics analysis also predicted a positive role for DDX21 in supporting several pathways of relevance for cancer." (PMID 40002164, 2025). "DDX21 contributes to the development of multiple human cancers, including breast cancer, gastric cancer, melanoma, colorectal cancer, and neuroblastoma, but its role in HCC has not been reported." (PMID 39952918, 2025). "LncRNAs have emerged as potential functional molecules for cancer diagnosis and treatment, with DDX21 identified as a downstream target of several lncRNAs involved in gastric carcinogenesis." (PMID 39769343, 2024). "DDX21 is often overexpressed in several cancers, where it contributes to tumorigenesis by affecting key biological processes such as ribosome biogenesis, transcription, genome stability, and cell cycle regulation." (PMID 39769343, 2024). "DDX21 exhibits diverse and context-dependent roles across cancer types, acting as both a promoter of tumor progression through genomic instability and cell cycle regulation and a suppressor of metastasis via the epigenetic repression of EMT-related genes." (PMID 39769343, 2024). "Future studies should aim to clarify the specific mechanisms of the activity of DDX21, advance the development of targeted therapies, and assess its clinical relevance across various cancer types and stages." (PMID 39769343, 2024). "In these cancers, DDX21 regulates tumor development primarily through its effects on transcription and ribosome biogenesis." (PMID 39769343, 2024). "The elevated expression of DDX21 has been observed in most cancers, where it influences tumorigenesis by affecting ribosome biogenesis, transcription, genome stability, and cell cycle regulation." (PMID 39769343, 2024). "As a complex molecular target, DDX21 warrants further research to elucidate its specific mechanisms of action in different cancer types." (PMID 39769343, 2024). "Ultimately, the identification of DDX21 as a promising biomarker across various cancer types offers significant potential for its use in disease detection, early intervention, prevention, and treatment strategies." (PMID 39769343, 2024). "In the context of cancer, research on DDX21 is relatively new, but studies have indicated that its expression is aberrant in certain tumors, and it is linked to tumor occurrence and progression." (PMID 37988222, 2023).
cancer (continued). "Since MCM5 which is essential for the initiation of DNA replication has been reported to associated with cancer cell proliferation and metastasis, we focused on the role of MCM5 in DDX21-dependent CRC regulation." (PMID 37029300, 2023). "DDX21 is involved in the carcinogenesis of various malignancies, but there has been no comprehensive research on its involvement in different types of cancer." (PMID 36505822, 2022). "In summary, our work clarified the potential role of DDX21 in tumor immunity and its prognostic value for a variety of cancers." (PMID 36505822, 2022). "We separated cancer cases into high-expression and low-expression categories based on DDX21 expression levels and evaluated the relationship between DDX21 expression and prognosis in patients with various tumors, primarily utilizing TCGA and GEO databases." (PMID 36505822, 2022). "The TIMER2 tool was used to examine the DDX21 expression status across diverse cancer types in TCGA database." (PMID 36505822, 2022). "We found that the DDX21 gene is significantly expressed in 13 cancers, and IHC analysis confirmed this trend at the protein level." (PMID 36505822, 2022). "In summary, these findings suggest that DDX21 acts as an oncogene in the progression of a number of cancers and is a viable predictor of cancer prognosis in practical applications." (PMID 36505822, 2022). "DDX21 protein was again found to be significantly overexpressed in cancer relative to matched benign mucosa." (PMID 33328538, 2020). "DEAD-box RNA helicase DDX21 (also named nucleolar RNA helicase 2) is a nuclear autoantigen with undefined roles in cancer." (PMID 33328538, 2020). "Consistent with our findings, a significant higher expression of lncRNA-ZFAS1 and DDX21 was observed in the vast majority of cancers, including CRC based on the TCGA dataset." (PMID 33202381, 2020). "DDX21 expression appeared to be more prevalent in stage I than in stage II cancer tissues, with the difference being statistically significant." (PMID 33328538, 2020). "Based on these discoveries, we derived that the expression levels of DDX21 showed tumor heterogeneity in various tumors and the molecular mechanism of DDX21 need to be precisely clarified in different cancers." (PMID 33202381, 2020). "Indeed, while DDX21 plays an oncogenic role in colorectal, gastric and other cancers, downregulation of its expression correlates with dismal prognosis in breast cancer and kidney renal papillary cell carcinoma." (PMID 40002164, 2025). "Indeed, the role of DDX21 in human cancers seems to be highly context-specific, with examples of both pro-tumoral and tumor-suppressive actions being reported." (PMID 40002164, 2025). "The results showed that DDX21 is related to “transcriptional misregulation in cancer”." (PMID 40301349, 2025). "Previous reports have shown that DDX21 acts as a tumor promoter in several cancers." (PMID 39952918, 2025). "Identifying DDX21 and other autoantigen markers in cancer tissues may provide a basis for developing more specific cancer immunotherapy strategies in the future." (PMID 39769343, 2024). "High expression of DDX21 was linked to poor prognosis in terms of OS for ACC (log-rank p = 0.00017), CESC (log-rank p = 0.017), KIRP (log-rank p = 0.037), MESO (log-rank p = 0.001), and PAAD (log-rank p = 0.0089) cancers based on TCGA data." (PMID 36505822, 2022). "Based on these findings, we hypothesize that DDX21 may exert a tumor-promoting effect in cancer by driving RNA metabolism and promoting ribosomal protein synthesis." (PMID 36505822, 2022). "In the present study, we employed the TIMER, CIBERSORT, CIBERSORT-ABS, QUANTISEQ, XCELL, MCPCOUNTER, and EPIC algorithms to explore the possible link between the infiltration level of different immune cells and DDX21 gene expression in various cancer types according to TCGA database." (PMID 36505822, 2022). "This pan-cancer study revealed the prognostic value and the oncogenic role of DDX21." (PMID 36505822, 2022).
cancer (continued). "DDX21 has recently been shown to be involved in various cancers." (PMID 33497018, 2021). "The mechanistic roles of DDX21 in cancers remain poorly understood and merit further investigation." (PMID 33328538, 2020). "All of these cancer cells displayed detectable but varying DDX21 protein expression levels." (PMID 25260534, 2014). "The level of DDX21 expression was associated with non-mucous histology in early cancer." (PMID 37988222, 2023). "Identification of DDX21 and other autoantigen markers in cancer tissues may pave the way for future development of more specific and more effective immunotherapy strategies against cancer." (PMID 33328538, 2020). "Additionally, while DDX21-driven genomic instability may enhance chemosensitivity in some cancers, its role in promoting autophagy and survival in others suggests opposing therapeutic implications, underscoring the need for precise, cancer-specific targeting strategies." (PMID 39769343, 2024). "SNORA74A activates PARP1-directed DExD-box helicase 21 (DDX21) ADP-ribosylation and increases the nuclear localization of DDX21 protein, thereby promoting ribosomal biogenesis and cancer cell growth." (PMID 36566215, 2022). "To investigate the functional mechanism of DDX21 in the occurrence of cancer, we used GEPIA2 to identify the top 100 genes in TCGA dataset with expression patterns comparable with DDX21." (PMID 36505822, 2022). "The protein network of unique cancer cell genes in the “cancer cells_vs_all-PDAC” group exhibited top 10 hub genes, including H4C6 (HIST1H4A or HIST1H4C), MYC, H3C12 (HIST1H3A or HIST1H3D), DDX21, USP7, RFC4, APEX1, CDK9, H2BC9 (HIST1H2BH), and NOP2." (PMID 40906153, 2025). "Furthermore, the MYC, DDX21, USP7, RFC4, APEX1, CDK9, and NOP2 of the “cancer cells_vs_all-PDAC” group play a critical role in the metabolic reprogramming of the PDAC, contributing to the poor prognosis of PDAC." (PMID 40906153, 2025). "Additionally, the TISCH2 indicated that all the hub-genes of cancer cells were upregulated in malignant cells, especially GAPDH, RHOA, TPI1, H4C6, DDX21, and APEX1, which showed considerably high expression levels in malignant cells." (PMID 40906153, 2025). "The ZFAS1/DDX21/POLR1B signaling regulation axis may also be a new biomarker for targeted CRC treatment, where ZFAS1 knockdown dramatically reduced cancer cell properties and increase apoptosis." (PMID 34262080, 2021). "Although this regulation pattern of RNA-protein interaction had been widely investigated, however, no study was reported between ZFAS1 and DDX21 in regard to cancers." (PMID 33202381, 2020). "DDX21 expression levels correlated with non-mucinous histology in early stage cancers but not with other clinicopathological features such as patient gender, age, tumor location, tumor grade, or mismatch repair status in any cancer stage." (PMID 33328538, 2020). "DDX21 protein levels were significantly higher in cancer cell lines (compared to nontransformed MCF10A cells) that proliferated faster, such as HCC1806, SKBR3, MDA-MB-231." (PMID 25260534, 2014). "Even though their detailed molecular mechanisms remain largely undiscovered, our report on DDX21 function underscores the potential importance and diversity of DEAD/DEAH helicases in promoting cancer and certainly warrants a broader evaluation of the activities of this protein family." (PMID 25260534, 2014). "This hypothesis is validated by our study that, since MCM5 is a phase separation-specific target of DDX21, we can suppress cancer metastasis by inhibiting MCM5 expression without disrupting DDX21 phase separation." (PMID 37029300, 2023). "In line with the molecular functions of the selected genes modulating transcription (BPTF, DDX21), protein translation (NOLC1, TCOF1), or nuclear import (KPNA2) it is feasible to speculate that restoring their cellular content in cancer cells could facilitate viral production." (PMID 34203557, 2021).
cancer (continued). "Based on this scoring, the cancer cohort was then divided into two groups, a positive (or high expression) group that showed positive nuclear DDX21 staining in ≥ 10% of cancer cells, and a negative (or low expression) group that showed negative staining or staining in < 10% of cancer cells." (PMID 33328538, 2020). "DDX21 is activated by ADP-ribosylation with PARP-1, and therefore PARP inhibitors can be used to indirectly suppress DDX21 and reduce cell proliferation even in cancer cells without defects in DNA repair machinery." (PMID 33804185, 2021).